INS (insulin)
Diseases named in the same sentence as INS in open-access papers (continued):
Sharing a sentence is not in itself a finding about the gene and the disease.
Hypoglycemia (continued). "There is evidence to suggest that increased sNRP1, seen here following insulin-induced transient hypoglycaemia but also as a consequence of strict glycemic control, might offer protection against COVID-19 disease severity." (PMID 34248841, 2021). "This reduced glucagon secretion during insulin-induced hypoglycemia by 60%." (PMID 34787082, 2021). "The limited increase in insulin dose in this study may have further contributed to the observed low incidence and rates of hypoglycaemia, as in the DUNE study." (PMID 33532606, 2021). "The potentially fatal cardiovascular effects of hypoglycaemia are not well understood and large animal models of the counter-regulatory responses and cardiovascular consequences of insulin-induced hypoglycaemia are needed to understand the mechanisms in humans." (PMID 33727615, 2021). "In fact, supplementing with carbohydrates has been shown to potentially be superior to bolus insulin reduction for prevention of hypoglycemia during physical activity, as was demonstrated in a group of adults with T1D engaging in moderate-intensity cycling for 45 min in one study." (PMID 34501920, 2021). "Other antidiabetic therapies when used as monotherapy or in combination therapy without insulin or sulfonylureas are rarely associated with hypoglycemia." (PMID 34067055, 2021). "SGLT2I- is unique in the capabilities thereof to lower blood sugar and inhibit insulin secretion independent of insulin, with no increase to the risk of hypoglycemia." (PMID 34341711, 2021). "Insulin therapy can save lives but requires daily use, increasing the risk of severe hypoglycemia, reducing but not avoiding other serious complications, including microvascular and macrovascular disease and death." (PMID 33574570, 2021). "In T2DM patients, the incidence rate of SH ranges from 0 to 0.73 episodes/patient-year in people with T2DM, with several variables recognized to influence the episodes of hypoglycemia such as age, disease duration, intensification of glycemic control, use of insulin or sulfonylureas." (PMID 34572493, 2021). "The peak of cortisol level in response to the insulin-induced hypoglycemia test was 9.4 μg/dl." (PMID 34007493, 2021). "Thus, due to precise and flexible dosage adjustment, the insulin pump can quickly control the blood glucose, reduce insulin dosage, and reduce the occurrence of hypoglycemia, which is an important means of intensive insulin therapy." (PMID 33483468, 2021). "Regarding our findings, by taking into consideration that lunch is the most important meal of the day, a more intensive insulin or anti-diabetic drug administration might lead to glycemic fluctuations and/or hypoglycemia." (PMID 33418926, 2021). "The rate of release of insulin reacted rapidly to increased glucose levels could be further enhanced by GOx, and induced hypoglycemia similar to that of subcutaneous injection or just insulin-charged microneedles." (PMID 34372008, 2021). "Sympathetic innervation of islets reciprocally regulates hormone release in response to hypoglycemia by inhibition of insulin release through activation of α2-adrenergic receptors (ADRA2A) on β-cells and stimulation of glucagon secretion by activation of β2-adrenergic receptors (ADRB2) on α-cells." (PMID 33753784, 2021). "However, no pre-mature death was observed in the animals as would be expected from severe hypoglycemia due to overexpression of insulin." (PMID 34862365, 2021). "Some studies have shown that with the use of an insulin pen instead of the use of a bottle and syringe in patients with DM2, adherence, glycemic control and lower incidence rates of hypoglycemia were obtained in the groups of patients treated with insulin pens instead of syringes." (PMID 34821614, 2021). "The intracellular calcium release elicited by ethanol may play a prominent role as a mechanism involved in cellular insulin release and the consequential observed hypoglycemia." (PMID 33467410, 2021).
Hypoglycemia (continued). "Severe hypoglycemia following attempts such as intensive insulin treatment has been reported." (PMID 35050147, 2021). "One serendipitous benefit of automated insulin pumps may be improved sleep resulting from improved glycemic control and reduced fear of nocturnal hypoglycemia." (PMID 33628834, 2021). "Thus, many patients are reluctant to start or adhere with a basal-bolus insulin regimen due to its complexity to administer and titrate, the need for multiple daily injections and a fear of hypoglycemia." (PMID 33776914, 2021). "The raising of the risk of hypoglycemia was reported as a negative effect of intensive insulin therapy in the DCCT trial." (PMID 34909088, 2021). "These settings can improve safety in insulin delivery and can help mitigate insulin stacking, which could lead to hypoglycemia." (PMID 37745178, 2021). "One reason this is of interest is that improved insulin adherence, insulin persistence, and lower hypoglycemia rates have been observed among patients who were initially insulin naive and who used pen devices at insulin initiation compared with those who used vials." (PMID 34636912, 2021). "These are diabetic treatment agents with a low risk of hypoglycemia because they facilitate the excretion of glucose in a hyperglycemic state without affecting insulin secretion." (PMID 34489627, 2021). "The main adverse reaction of insulin treatment is hypoglycemia, especially in intensified treatment where insufficient calorie uptake or physical exertion could be possible triggers." (PMID 33467194, 2021). "The authors concluded that an additional 30% of insulin resulted in the best result and almost return to baseline after 4 h without increased risk of hypoglycaemia (higher risk at 145% and 160% bolus insulin), based on CHC calculation." (PMID 34684559, 2021). "However, a large body of literature indicates that patients with DM have insufficient knowledge about hypoglycemia and insulin use." (PMID 34497858, 2021). "This may not truly represent real-world use of the product, as patients in the trials received high doses of insulin to achieve hypoglycemia; this might have limited their ability to see a rise in glucose or determine effectiveness." (PMID 34638984, 2021). "Despite that, insulin-induced hypoglycemia and even glucose deprivation did not cause a change in microglia morphology from ramified to ameboid shape." (PMID 34884473, 2021). "Compared with insulin group, glyburide group had higher prevalence of neonatal hypoglycemia." (PMID 34641848, 2021). "Combined with the glucose tolerance test, it was suggested that hypoglycemia was not caused by insulin secretion." (PMID 35049191, 2021). "BBR increases high-glucose-dependent insulin secretion in humans and is an excellent insulin secretagogue without the potential side effect of causing hypoglycemia." (PMID 34556670, 2021). "Owing to the reduced risk of symptomatic and nocturnal hypoglycemia of LAIA versus IAHI as demonstrated in clinical studies, LAIA is generally preferable in clinical practice compared to IAHI, such as human neutral protamine Hagedorn (NPH) insulin." (PMID 33602950, 2021). "Varying insulin sensitivity is also a major factor in misanalysing the amount of bolus insulin needed and might lead to postprandial hypoglycemia." (PMID 33466659, 2021). "Adverse effects related to insulin use include weight gain and hypoglycemia." (PMID 33435250, 2021). "The excessive use of basal insulin in our study could have also contributed to the high rates of hypoglycemia in patients using insulin analogues." (PMID 33905628, 2021). "Moreover, C-peptide infusion also doubled glucagon secretion in these animals during insulin-induced hypoglycemia, which increased net HGP by 75% and lowered the need for exogenous glucose infusion." (PMID 34003799, 2021).
Hypoglycemia (continued). "Moreover, C-peptide infusion during insulin-induced hypoglycemia doubled glucagon secretion and increased net hepatic glucose output by 75%, thereby lowering the need for exogenous glucose to maintain glycemia." (PMID 34003799, 2021). "Furthermore, acute insulin-induced hypoglycemia has been demonstrated to increase vWF levels in humans, likely the consequence of the hypoglycemia-induced increase in corticosterone levels or endothelial dysfunction, and enhancing platelet aggregation." (PMID 34091064, 2021). "Two broad categories are of particular concern: insulin secretagogues (insulin-releasing medications) with a potential adverse effect of hypoglycemia and non-insulin secretagogues that rarely cause hypoglycemia." (PMID 33441946, 2021). "Conversely, a higher proportion of patients in the insulin group reported hypoglycemia, which may be attributed to greater fluctuations in glycemic control with insulin than with incretin-based therapy." (PMID 34275099, 2021). "Multivariable analysis showed that increase in body weight (OR: 0.969; 95% CI: 0.947‐0.992; P = .008) reduces the odds, whereas the increase in basal insulin daily dose (OR: 1.024; 95% CI: 0.019‐1.051; P = .005) increases the odds of symptomatic hypoglycaemia (page 4 and 5)." (PMID 33532606, 2021). "Sixty-seven patients (64.43%) still had recurrent hypoglycemia after insulin was discontinued." (PMID 33827670, 2021). "Careful research, clinician experience, and guideline changes may, by themselves, be insufficient to avoid overtreatment of hypoglycemia when preceded by insulin suspension." (PMID 33535013, 2021). "Interestingly, in our bolus study, QTc-interval increased only five minutes after insulin dosing, and before reaching hypoglycaemia target." (PMID 33727615, 2021). "Soluble isoforms of NRP1 (sNRP1) also exist without transmembrane or cytoplasmic domains, expressing only the extracellular domains which allow them to bind NRP1 ligands; therefore, the plasma levels of NRP1 ligands (VEGFA and SEMA3A) were determined in response to insulin-induced hypoglycemia." (PMID 34248841, 2021). "In addition, randomized controlled trials have found that IDeg is associated with significantly lower rates of severe hypoglycemia and nocturnal hypoglycemia than is insulin glargine U-100 in patients with T2D while providing equivalent glycemic control." (PMID 33550540, 2021). "The initiation of prophylactic therapy with pilocarpine, metoprolol, or diltiazem may be useful in preventing the pro-arrhythmic effects of insulin-induced hypoglycemia." (PMID 33898141, 2021). "Remaining glycemic ranges, risk of hypoglycemia and insulin therapy were not significantly different in comparison of the type of therapy (p > 0.05)." (PMID 34295305, 2021). "In patients with T2DM, there is reduced insulin secretion during the first phase and extended insulin secretion during the second phase, a fact that may also lead to hypoglycemia." (PMID 33418926, 2021). "The important findings of the study are as follows: chronic MLQP and MLP diets (i) profoundly reduced the BWs by lowering LBM and fat mass, and by promoting hypermetabolism; and (ii) enhanced insulin sensitivity by promoting hypoglycemia and hypoinsulinemia in the offspring." (PMID 34836384, 2021). "Premixed insulins are associated with greater HbA1c reductions than basal insulin alone without increasing overall hypoglycemia or body weight; nevertheless, they do increase mild hypoglycemia." (PMID 34063071, 2021). "The reason for diminished hypoglycemia/insulin-induced copeptin release in T1D is unknown, but we speculate that recurrent hypoglycemia in patients with T1D may result in changes in glucose and/or insulin sensitivity in the A1/C1 region." (PMID 34787082, 2021). "Both therapies yielded comparable metabolic control and treatment satisfaction but CSII was associated with higher incidence of non-severe hypoglycaemia and lower insulin dosage." (PMID 34301317, 2021).
Hypoglycemia (continued). "It demonstrated that daily oral administration of up to 67.5 mg of insulin to healthy, genetically at-risk, islet autoantibody-negative children at 6 months to 2 years of age was well tolerated without signs of hypoglycaemia." (PMID 33515070, 2021). "The risk of hypoglycaemia could further be reduced when used closed loop systems that suspend insulin before hypoglycaemia." (PMID 34684559, 2021). "Further intraperitoneal injection of short-acting insulin induced severe hypoglycemia." (PMID 34899278, 2021). "Moreover, metformin activates hypoglycemia by decreasing intestinal glucose absorption and hepatic glycogenesis to improve glucose uptake and utilizing peripheral tissues that enhance insulin sensitivity." (PMID 34203830, 2021). "Although no conclusions can be drawn from these anecdotal cases, frequent hypoglycemia may add to the atrial fibrillation burden in insulin-treated patients with paroxysmal atrial fibrillation." (PMID 34085953, 2021). "An episode of hypoglycemia induces an adaptive counter-regulatory response, which involves enhanced glucagon, epinephrine, cortisol and growth hormone secretion; the suppression of insulin release; and the modulation of the autonomic nervous system." (PMID 34830301, 2021). "Our population was not yet on insulin therapy, which made it safe and feasible to implement a low-calorie diet without changes of medication throughout the study, thus minimizing hypoglycemia risk." (PMID 33839905, 2021). "The empagliflozin-basal insulin group had a lower total number of hypoglycaemic episodes, patients with 1 or ≥2 episodes, hypoglycaemia incidence rate, and patients with any level 1 hypoglycaemia." (PMID 34441835, 2021). "DS20060511 reduced the blood glucose levels in obese diabetic mice, without causing hyperphagia, body weight gain, or hypoglycemia, and without increasing insulin secretion." (PMID 34417555, 2021). "Furthermore, cases have been reported of sudden hypoglycemia occurrences following multidose insulin injections." (PMID 33466845, 2021). "Calculation of the glucose infusion rate (GIR) to insure this is not excessive, is critical but the use of insulin is often helpful in the extremely preterm infant, but is associated with an increased risk of hypoglycaemia." (PMID 34368024, 2021). "Then, insulin/proinsulin dissociates from these endogenous antibodies, giving rise to hypoglycemia." (PMID 33827670, 2021). "Furthermore, 212 of 1129 (18.8%) participants who were administered with twice-daily IDegAsp and 463 of 1929 (31.4%) participants who were administered with conventional premixed insulin experienced at least one nocturnal hypoglycemia event." (PMID 34564455, 2021). "CSII and ICT yielded comparable metabolic control and treatment satisfaction but CSII was associated with higher incidence of non-severe hypoglycaemia and lower insulin dosage." (PMID 34301317, 2021). "SGLT2i as an add-on therapy to insulin improved glycemic control and body weight and decreased the required dose of insulin without increasing the risk of hypoglycemia." (PMID 33651228, 2021). "Because insulin-induced hypoglycemia is usually limited by the counter-regulatory mechanism that is initiated in part by the brain including the VMH neurons, our data may indicate impaired counter-regulation to the insulin stimulus." (PMID 33974562, 2021). "Colesevelam possesses antidiabetic properties, which could potentiate sulphonylurea or insulin-induced hypoglycemia; clinically significant hypoglycemia, as a side effect to bile acid sequestrants, may be under-recognized in clinical practice." (PMID 34691455, 2021). "This has improved with long-acting insulin analogues and insulin pumps, and may improve further with newer hybrid closed loop technologies, which can minimize hypoglycemia through automated basal rate adjustment." (PMID 33828529, 2021). "Insulin-induced hypoglycemia (from 8 mM to 4 mM) increased circulating glucagon levels tenfold." (PMID 34787082, 2021).
Hypoglycemia (continued). "However, during the telephone calls with the CNS, 38% (15/39) of patients reported symptoms of hypoglycemia, demonstrating the need for support for people commencing insulin therapy." (PMID 32406854, 2020). "Insulin-induced hypoglycemia in nondiabetic male subjects was associated with increased proinflammatory cytokines (TNF-α, IL-1β, IL-6, and IL-8), indicators of lipid peroxidation and ROS production." (PMID 33123598, 2020). "The reduced late insulin response in Hmox1-/- mice could be induced by insulin antagonistic pathways in response to hypoglycemia such as hepatic gluconeogenesis, alterations in the hypothalamic–pituitary–adrenal axis and increased inflammatory cytokines." (PMID 32992485, 2020). "However, high levels of circulating insulin, such as that found in HI patients, inhibits ketogenesis and thereby removes this neuro-protective response to hypoglycemia." (PMID 32735622, 2020). "Insulin pumps or glucose sensors appeared cost-effective, especially in populations with the most to gain from such interventions such as those with higher HbA1c levels and rates of hypoglycaemia." (PMID 32746937, 2020). "Additionally, parents reported concerns regarding the child’s hypoglycemia and administering insulin, and their worries regarding hypoglycemia were associated with anxiety and negative emotions." (PMID 33218148, 2020). "Heterogeneous PEC dispersions might have resulted in the high intra-batch variabilities that were observed in hypoglycaemia and variable serum insulin levels." (PMID 32178442, 2020). "Also, the STZ-treated ghrelin-KO mice exhibited attenuated plasma epinephrine and norepinephrine responses to the insulin-induced hypoglycemia." (PMID 33042003, 2020). "While all participants were provided notebooks and pens and asked to keep a record of insulin injections and symptoms of hypoglycaemia, only two returned with recorded information, so these data could not be included in the analysis." (PMID 32704558, 2020). "FGF1 showed a robust glucose homeostasis profile, lowed the plasma insulin of db/db mice and did not cause hypoglycaemia and changeable plasma glucagon after chronic administration." (PMID 32979037, 2020). "Thus, according to the results collected, dexamethasone provides a secretory response widely comparable to insulin-induced hypoglycemia in terms of induced GH peaks and overall potency of the test." (PMID 33362716, 2020). "Besides, we noticed that during CSII therapy, after reaching the normal glucose standard, some patients showed repeated mild hypoglycemia episodes despite the fact that their insulin doses decreased sharply." (PMID 32149152, 2020). "However, it is unclear how soon blood glucose falls after insulin administration, and it has recently become clear that hypoglycemia has a greater prognostic effect." (PMID 33005854, 2020). "In addition to the influence of insulin itself, prelunch hypoglycemia is related to the eating habits of the Chinese." (PMID 33015194, 2020). "However, despite taking more carbohydrates and less insulin, a rigorous physical exercise can still derive the blood glucose dynamics into the hypoglycemia region." (PMID 32784179, 2020). "However, a paracrine role of insulin in the physiologically important glucagon counterregulation of hypoglycemia seems unlikely because insulin release is basal under such conditions." (PMID 32156704, 2020). "Existing automated DSSs are designed to provide recommendations to people with T1D regarding insulin doses, anticipated hypoglycemia, and modifications to daily behaviors that may improve their glycemic outcomes." (PMID 32517068, 2020). "These mice have more profound hypoglycemia with insulin treatment than control animals." (PMID 33148883, 2020). "Similarly, both repeated 2DG and repeated insulin-induced hypoglycemia significantly reduced GHRH dendritic spine density." (PMID 33148883, 2020).